ANGPTL1 (angiopoietin like 1)
Diseases named in the same sentence as ANGPTL1 in open-access papers (continued):
Sharing a sentence is not in itself a finding about the gene and the disease.
tumor (continued). "ANGPTL1 functions as an anti-angiogenic agent and a tumour suppressor." (PMID 40475773, 2025). "Additionally, M2 macrophages downregulate the angiopoietin-like protein 1 (ANGPTL1), leading to increased vascular permeability in sinusoidal vessels for the arrival of more tumoural cells." (PMID 39430087, 2024). "Studies have shown that ANGPTL1 can act as an anti-angiogenic factor and a tumor suppressor." (PMID 36101384, 2022). "For instance, ANGPTL1 has been proven to inhibit tumor metastasis in several cancers." (PMID 36568384, 2022). "In comparison, less fluorescence was detected in the liver educated by ANGPTL1-Exo (P < 0.001), which indicated that exosomal ANGPTL1 could impede the vascular leakiness in liver PMNs induced by tumor-derived exosomes." (PMID 33413536, 2021). "Moreover, Gas5 spongs miR-182 can up-regulate anti-metastatic protein Angiopoietin Like 1 (ANGPTL1) expression and then inhibit tumor metastasis, which can play a crucial role in the therapeutic intervention against the progression of HCC." (PMID 34758879, 2021). "That is why the inhibition of cancer cell growth and tumor metastasis is a major effect of ANGPTL1." (PMID 34445141, 2021). "Firstly, ANGPTL1 may play an essential role in tumor inhibition by balancing angiogenesis and permeability." (PMID 32410376, 2020). "ANGPTL1 has anti-angiogenic activity in vitro and tumor suppressive activity in vivo." (PMID 29389861, 2018). "Together, these studies congruously characterized ANGPTL1 as a tumor suppressor gene in cancer." (PMID 28606130, 2017). "Indeed, ANGPTL1 transcript has been found to be down-regulated in several tumor specimens, including lung, prostate, kidney, thyroid, and urinary bladder cancers." (PMID 24478758, 2014). "In addition, a clinicopathological association study of 122 pairs of liver cancer samples was conducted and found that low expression of ANGPTL1 was significantly associated with serum AFP levels, vascular invasion, poor differentiation, metastasis, and tumor thrombus." (PMID 36156125, 2022). "Therefore, ANGPTL1 acts as a general tumor suppressor gene in human cancers." (PMID 34685578, 2021). "Thus, based on ANGPTL1 in vitro activity and on expression profile, it was postulated that ANGPTL1 could play an inhibitory role in tumor progression." (PMID 29389861, 2018). "Moreover, results from the ectopic overexpression studies suggest that ANGPTL1 may play an essential role in tumor inhibition by affecting different angiogenic processes necessary for tumor growth." (PMID 29389861, 2018). "Normal tissues expressed ANGPTL1 and ANGPTL3, whereas tumor tissues expressed median and low levels." (PMID 35692877, 2022). "We found that ANGPTL1, ANGPTL3, ANGPTL4, ANGPTL6, and ANGPTL7 were differentially expressed between tumor and normal tissues." (PMID 35692877, 2022). "And a further exploration of ANGPTL1’s effect on cancer cells’ behavior and the TME uncovers a multifunctional tumor suppressor." (PMID 36156125, 2022). "Early studies showed that Angiopoietin-like protein 1 (ANGPTL1) acts as an antiangiogenic factor and a tumor suppressor." (PMID 33413536, 2021). "To investigate the effect of ANGPTL1 on the metastatic potential of CRC cells, we employed a hemi-spleen liver metastasis model, in which tumor cells suspensions were injected into a part of the spleen, with successive hemi-splenectomy." (PMID 28606130, 2017). "ANGPTL1 is prominently expressed in effector memory CD4 T cells and myeloid-derived suppressor cells (MDSCs), potentially contributing to immunosuppression and the regulation of the tumour microenvironment." (PMID 40475773, 2025). "Given the reduced ANGPTL1/TEK signaling in MDA-MB-231 VMT and clinical TNBC, which correlates with disrupted vasculature, our objective was to investigate the potential benefits of increasing TEK signaling in the tumor EC by blocking VE-PTP with razuprotafib." (PMID 38183074, 2024).
tumor (continued). "The protein of ANGPTL1 could impede vascular leakiness to inhibit CRC‐LM; however, the level of ANGPTL1 is decreased in the EVs from CRC tumour tissues compared to that in normal tissues." (PMID 36068649, 2022). "Moreover, the significant downregulation of ANGPT2, ANGPT2, ANGPTL1, ANGPTL4, and ANGPTL6 was found in tumor-adjacent tissues." (PMID 34685578, 2021). "To determine whether ANGPTLs are associated with sorafenib sensitivity in RCCs, we examined the mRNA expression levels of ANGPTL1-8 in 7 RCC cell lines, as well as a set of pre-treated tumour tissues from a cohort of RCC patients that presented with distinct responses to sorafenib therapy." (PMID 30033448, 2018).
cancer (26 papers, 2007 to 2025). A tumor composed of atypical neoplastic, often pleomorphic cells that invade other tissues. "Subsequently, potential cancer-associated miRNA clusters upstream of ANGPTL1, SOCS3, ACACB, and EHHADH were predicted via integrated cross-analysis using multi-databases, including miRDB, TargetScan, RNAInter, and miRWalk." (PMID 40426998, 2025). "Both genes are connected with other genes notably deregulated in cancer as ANGPTL1, ADAMTSL2, PELI2 and EPCAM." (PMID 41231825, 2025). "In vitro experiments provided experimental support that ANGPTL1 plays an anti-cancer role, inhibiting the proliferation, migration, and invasion of HNSCC cells." (PMID 40475773, 2025). "These genes were also connected with other genes notably deregulated in cancer as ANGPTL1, ADAMTSL2, PELI2 and EPCAM." (PMID 41231825, 2025). "What is more, Forkhead box O-3a (Foxo3a)–SRY-related HMG-box-2 (Sox2) axis was first explored as the mechanism of ANGPTL1 regulated cancer migration, invasion, and stemness." (PMID 36156125, 2022). "The mean expression level [measured by Log2(counts)] of ANGPTL1/2/4 was 9.982, 11.690, and 9.548 in normal tissue and 7.142, 11.930, and 8.792 in cancer tissue, respectively." (PMID 32410376, 2020). "More specifically, ANGPTL1 has been shown to reduce migratory and invasive abilities of different cancer cell lines in vitro and to suppress the EMT." (PMID 29389861, 2018). "ANGPTL1 can suppress SLUG (SNAIL-related zinc-finger transcription factor) to inhibit cancer cell motility." (PMID 29389861, 2018). "For example, ANGPTL1 can suppress SLUG to inhibit cancer cell motility, and ANGPTL3 plays an important role in cancer growth and invasion." (PMID 26056041, 2015). "It has been shown that ANGPTL1 affects the phosphorylation of intracellular signaling kinases in cancer cells, like focal adhesion kinase (FAK), AKT and ERK1/251." (PMID 25970467, 2015). "Regarding other putative targets, such as SEMA6D, RGS2 and ANGPTL1, their involvement and modulation in cancer has been demonstrated but their interaction with miR-182 have yet to be explored." (PMID 25115394, 2014). "Above findings made ANGPTL1 more attractive either as cancer prognostic or predictive biomarkers." (PMID 36156125, 2022). "ANGPTL1 has been reported to play a critical role in cancer progression and metastasis." (PMID 36156125, 2022). "This work demonstrated that the CRC liver metastasis and cancer stemness regulated by ANGPTL1 shared the same pathway—ANGPTL1/Foxo3a/Sox2, but if there was an association between the two phenotypes is unknown." (PMID 36156125, 2022). "For example, a study indicated that ANGPTL1 could inhibit sorafenib resistance and cancer stemness in HCC cells through acting as a Met receptor inhibitor." (PMID 32410376, 2020). "Thus suggesting that ANGPTL1 inhibits motility and invasiveness of cancer cells." (PMID 29389861, 2018). "Among them, only six genes—MMP11, ANGPTL1, GSTM5, IQGAP3, UHRF1, and CCBE1—were shared across all analyzed carcinomas." (PMID 39596491, 2024). "The common (pan-cancer) genes are MMP11 (+), C7 (-), ANGPTL1 (-), UBE2C (+), IQGAP3 (+) and ADH1B (-)." (PMID 36802377, 2023). "We further found that ANGPTL1, ANGPTL3, ANGPTL4, and ANGPTL8 were significantly highly expressed in HCC cell lines than other types of cancer cell lines (p < 0.05)." (PMID 35692877, 2022). "More recently TC Kuo and colleagues validated a mechanism by which ANGPTL1 through integrin α1β1, miR-630 and SLUG pathway induces mesenchymal-to-epithelial transition (MET) allowing cancer cells to regain epithelial properties." (PMID 29389861, 2018). "In summary, we provide clinical evidence that ANGPTL1 expression is down-regulated in CRC tissues and inversely correlated with survival in patients with cancer." (PMID 28606130, 2017). "Among them, we focused on Angiopoietin-like protein 1 (ANGPTL1), which was down-regulated in 87.5% (14/16) of included cancer types." (PMID 28606130, 2017).
cancer (continued). "ANGPTL1 overexpression inhibits the MET receptor-AKT/ERK-Egr-1-Slug signaling cascade, repressing the epithelial–mesenchymal transition and thereby counteracting sorafenib resistance and cancer stemness in HCC cells." (PMID 34925311, 2021). "There is a significant reduction in the expression of ANGPTL1, which has anti-angiogenic properties, in favor of ANGPTL2, with pro-angiogenic properties, due to which, there is an enhanced angiogenesis supporting the development of cancer and its metastasis." (PMID 34445141, 2021). "The low expression of ANGPTL1 in CRC and many other cancer types suggested that it was a potential suppressor of cancer and may be associated with CRC initiation and progression." (PMID 28606130, 2017). "Thirdly, ANGPTL1 could induce mesenchymal‐to‐epithelial transition (MET) through integrin α1β1, miR‐630, and SLUG (SNAIL‐related zinc‐finger transcription factor) pathway, thus allow cancer cells to regain epithelial properties." (PMID 32410376, 2020). "None of the six genes (MMP11, ANGPTL1, GSTM5, IQGAP3, UHRF1, and CCBE1) have previously been categorized as carcinoma biomarkers collectively." (PMID 39596491, 2024). "Unlike ANGPTL1, ANGPTL2 is better acknowledged for its adverse pro-inflammatory properties and its contribution in cancer, diabetes, atherosclerosis, metabolic disorders and many other chronic diseases." (PMID 29389861, 2018).
ANGPTL1 also shares sentences with these, for which no sentence is quoted: breast invasive carcinoma (1 paper); breast tumor (1); glaucoma (1); glioma (1); infection (1); Obesity (1); osteoporosis (1); pancreatic cancer (1); squamous cell carcinoma (1); type 2 diabetes mellitus (1); urinary bladder cancer (1).